ILKAP (ILK associated serine/threonine phosphatase)
Description:
Protein phosphatase that may play a role in regulation of cell cycle progression via dephosphorylation of its substrates whose appropriate phosphorylation states might be crucial for cell proliferation. Selectively associates with integrin linked kinase (ILK), to modulate cell adhesion and growth factor signaling. Inhibits the ILK-GSK3B signaling axis and may play an important role in inhibiting oncogenic transformation.
Synonyms: DKFZP434J2031; FLJ10181; PPM1O; ILKAP2; ILKAP3; PP2C-DELTA; PP2CD
Tractability: PROTAC: ubiquitination databases record sites on it; its protein half-life has been measured.
Target class: Protein Phosphatase; Phosphatase; Serine/threonine protein phosphatase; Enzyme
Gene: Protein-coding gene on chromosome 2 (238,170,400 to 238,203,756, reverse strand). Ensembl gene ENSG00000132323.
Subcellular location: Cytoplasm
Gene Ontology:
Molecular function: protein binding; cation binding; protein serine/threonine phosphatase activity
Cellular component: cytoplasm
Genetic constraint (gnomAD): Loss-of-function variants: 9 observed, 41.35 expected, observed/expected ratio (o/e) 0.22, 90% interval 0.13 to 0.38. The upper end of that interval is the gene's LOEUF score, 0.38, which puts it in group 1 of 6, group 1 being the genes least tolerant of losing a copy. Missense variants: 295 observed, 442.79 expected, observed/expected ratio (o/e) 0.67, 90% interval 0.61 to 0.73. Synonymous variants: 146 observed, 169.18 expected, observed/expected ratio (o/e) 0.86, 90% interval 0.75 to 0.99.
Homologues: Orthologues: chimpanzee ILKAP (100% identical), macaque ILKAP (99% identical), dog ILKAP (97% identical), mouse Ilkap (95% identical), rat Ilkap (95% identical), guinea pig ILKAP (93% identical), rabbit ILKAP (91% identical), pig ILKAP (79% identical), tropical clawed frog ilkap (57% identical), zebrafish ilkap (55% identical), Caenorhabditis elegans ilkp-1 (32% identical). Paralogues in human: PPM1F (28% identical), PPM1E (27% identical), PPM1L (23% identical), PPM1A (22% identical), PPM1B (22% identical), PPM1G (22% identical), PPM1M (21% identical), PPM1N (21% identical), PPM1K (21% identical), PPM1H (20% identical), PPM1D (19% identical), PPM1J (18% identical), and 4 more.
Diseases named in the same sentence as ILKAP in open-access papers:
ILKAP is named in the same sentence as 10 diseases in open-access papers, as found by Europe PMC text mining. Sharing a sentence is not in itself a finding about the gene and the disease. The quoted sentences say what the papers report.
gastric cancer (2 papers, 2017 to 2022). A primary or metastatic malignant neoplasm involving the stomach. "Taken together, these results indicated that ectopic expression of MAEL contributes to increased p38, CHK1 and RSK2 phosphorylation by inhibiting ILKAP in gastric cancer cells." (PMID 29371914, 2017). "Based on our findings, MAEL overexpression contributes to the depression of ILKAP in gastric cancer." (PMID 29371914, 2017).
bladder cancer (1 paper, 2021). "MAEL has different molecular mechanisms in different tumor types in which it activates the AKT/GSK-3b/SNAIL signaling in HCC, inhibits the E-cadherin in CRC, inhibits the MTSS1 in bladder cancer, and inhibits ILKAP tumor suppressor in GC." (PMID 33902648, 2021).
breast carcinoma (1 paper, 2022). "qRT-PCR of the relative expression of ILKAP between breast cancer tissues and paired adjacent normal tissues from Shanghai Tenth Hospital corresponded to the results of the database (Student’s t test, p < 0.05)." (PMID 35383130, 2022). "Similarly, we found that circ_6014 has higher expression in breast cancer tissues, which corresponded to the results that ILKAP is highly expressed in breast cancer tissues (Student’s t test, p < 0.05)." (PMID 35383130, 2022). "Importantly, the fold changes of circ_6014 in breast cancer tissues were positively correlated with those of ILKAP (Y = 1.120X + 8.484, R2 = 0.3492, p = 0.334)." (PMID 35383130, 2022). "To confirm the existence and stability of circ_6014 in breast cancer, we treated MDA-MB-231 and MCF-7 cells with actinomycin D, which can inhibit transcription, and observed that the level of linear ILKAP was decreased, while the circ_6014 level was maintained over time." (PMID 35383130, 2022).
glioblastoma (1 paper, 2015). The most malignant astrocytic tumor (WHO grade IV). "We found that β1 integrin as well as the integrin-associated proteins PINCH1 and ILK were mainly located in focal adhesions of glioblastoma cells, whereas ILKAP was expressed in the cytoplasm and nucleus." (PMID 26460618, 2015). "To analyze the impact of PINCH1, ILK and ILKAP on cell survival, we performed efficient siRNA-mediated depletion in four different glioblastoma cell lines." (PMID 26460618, 2015).
melanoma (1 paper, 2014). A malignant, usually aggressive tumor composed of atypical, neoplastic melanocytes. "After genotyping 1,883 patients with melanoma and 1,358 control subjects, one SNP in intron 3 of ILKAP gene (rs6431588) was associated with increased risk of developing MM in the Spanish population (Fisher’s test p-value = 5×10−4)." (PMID 24743186, 2014). "Additionally, a second SNP (rs6431588) located on ILKAP was found to be associated with melanoma after considering a combined set of 1,883 MM cases and 1,358 disease-free controls." (PMID 24743186, 2014). "The results showed a weak reduction in the ANXA5 gene expression and a significant decreased gene expression of ILKAP (p-value <0.05 after applying Student’s t-test) in the melanoma cell lines studied in comparison with primary melanocytes." (PMID 24743186, 2014). "In order to confirm an alteration in the expression levels of ANXA5 and ILKAP in MM, quantitative measurement of these genes’ expression was investigated in 10 melanoma cell lines and 3 primary melanocytes using quantitative real time PCR." (PMID 24743186, 2014). "We also have experimentally observed that the levels of ILKAP gene expression decrease in melanoma cells compared to normal melanocytes." (PMID 24743186, 2014). "Furthermore, the biological relevance of these genes in MM is supported by in vitro experiments, which show a decrease in the transcription levels of ANXA5 and ILKAP in melanoma cells compared to normal melanocytes." (PMID 24743186, 2014). "Additionally, the results obtained from previous 2D-PAGE assays made in our laboratory suggested a decrease of both proteins ILKAP and Annexin A5 in melanoma cell lines compared to primary melanocytes." (PMID 24743186, 2014).
meningioma (1 paper, 2020). A generally slow growing tumor attached to the dura mater. "The global proteomic analysis of meningioma patients in the current study revealed perturbations in several components of Integrin including ITGAV, ITGB2, ITGA2B, and ILKAP." (PMID 32974197, 2020).
ovarian carcinoma (1 paper, 2020). A malignant neoplasm originating from the surface ovarian epithelium. "In fact, studies in platinum-resistant ovarian cancer have shown that ILKAP, a phosphatase which inactivates ILK, is downregulated by cisplatin treatment, and that silencing ILKAP increases ILK activation and protects cells from cisplatin-induced apoptosis." (PMID 32260415, 2020).
ovarian tumor (1 paper, 2023). "In the context of cancer, ILKAP was described to regulate the susceptibility of ovarian tumor cells to cisplatin, a platinum-based anti-cancer drug, but never associated with antigen-specific tumor killing by CTLs." (PMID 37732732, 2023).
tumor (5 papers, 2007 to 2023). "Taken together, these results show that ILKAP deletion enhances tumor killing independently of increasing sensitivity to IFNγ or TNF." (PMID 37732732, 2023). "The depletion of ILKAP induced increased tumor sensitivity to antigen-specific CTL killing in both cell lines which correlated with remaining expression." (PMID 37732732, 2023). "To validate the role of ILKAP in antigen-dependent tumor killing by CTLs, we disrupted gene expression with multiple sgRNAs in HCT 116 and Panc-1 cell lines." (PMID 37732732, 2023). "Our screens uncovered the role of ILKAP in protecting tumor cells from antigen specific CTL killing." (PMID 37732732, 2023). "Our screens showed that depletion of ILKAP leads to more tumor killing and activation of ILKAP expression to more resistance to CTL killing." (PMID 37732732, 2023). "Stimulation of ILKAP KO cells with IFN-γ and TNFα revealed that ILKAP-mediated tumor protection against CTL killing is independent from controlling INF-γ or TNFα sensitivity, changing PD-L1 levels and regulating antigen presentation." (PMID 37732732, 2023). "ILKAP has been found to play tumor suppressive roles by catalyzing the dephosphorylation of some oncogenic kinases, such as RSK2." (PMID 29371914, 2017). "When the tumor volumes reached 50–100 mm3, adenoviruses expressing ILKAP or GFP were injected into the tumors." (PMID 29371914, 2017). "Further studies are needed to investigate how ILKAP controls tumor killing by CTLs." (PMID 37732732, 2023). "Our approach uncovered ILKAP as novel regulator of tumor sensitivity to CTL killing." (PMID 37732732, 2023). "To investigate if ILKAP induces tumor resistance to CTL killing through a mechanism dependent on regulating IFN-γ or TNFα sensitivity, we stimulated ILKAP KO HCT 116 clone with IFN-γ or TNFα." (PMID 37732732, 2023). "The effect of ILKAP depletion and basal expression in Panc-1 cells on CTL-mediated tumor killing was more moderate compared to HCT 116 cells." (PMID 37732732, 2023). "In addition to PP2Cα and PP2Cβ, the recently identified PP2Cs ILKAP and PHLPP have also been implicated in growth regulation; the former has been shown to negatively affect proliferation and malignant transformation, and the latter to promote apoptosis and to inhibit tumor growth." (PMID 17941990, 2007). "Moreover, in a xenograft tumor mouse model, we showed that silencing MAEL expression or intratumorally injecting adenoviruses expressing ILKAP suppresses tumor growth." (PMID 29371914, 2017).
cancer (1 paper, 2023). A tumor composed of atypical neoplastic, often pleomorphic cells that invade other tissues. "ILKAP is a protein serine/threonine phosphatase of the PP2C family linked to cancer through phosphorylation of integrin-linked kinase (ILK) thereby modulating downstream integrin signaling." (PMID 37732732, 2023).